PGK1 (phosphoglycerate kinase 1)
Diseases named in the same sentence as PGK1 in open-access papers (continued):
Sharing a sentence is not in itself a finding about the gene and the disease.
hepatocellular carcinoma (23 papers, 2010 to 2026). A malignant tumor that arises from hepatocytes. "A recent study demonstrated that the lncRNA associated with microvascular invasion in hepatocellular carcinoma (lncRNA-MVIH) directly inhibits secretion of phosphoglycerate kinase 1 (PGK1)." (PMID 24346158, 2014). "PGK1 is highly expressed in hepatocellular carcinoma, and the silencing of PGK1 reduces cancer cell proliferation and metastasis." (PMID 33747900, 2021). "In vitro and in vivo studies showed that knockdown of PGK1 reduced proliferation and metastasis of SNU449 and HCCLM3 cells, indicating a driving role of PGK1 in hepatocellular carcinoma progression." (PMID 32028979, 2020). "Conversely, depletion of PGK1 with shRNA in hepatocellular carcinoma (HCC), resulted in a significant decrease in tumour proliferation, reversal of extracellular acidification and impairment of cancer cell glycolysis." (PMID 31198853, 2019). "All these findings indicate the possibility that PGK1 can be a biomarker in the treatment of hepatocellular carcinoma." (PMID 28749413, 2017). "We observed a significant overexpression of PGK1 in hepatocellular carcinoma tissues, and a correlation between PGK1 expression and poor survival of hepatocellular carcinoma patients." (PMID 28749413, 2017). "Our results revealed a new effect of PGK1, which can provide a new treatment strategy for hepatocellular carcinoma, as PGK1 is used to indicate the prognosis of hepatocellular carcinoma (HCC)." (PMID 28749413, 2017). "MVIH expression is high in hepatocellular carcinomas compared to normal tissues and targets phosphoglycerate kinase 1 (PGK1), a glycolytic enzyme that can inhibit angiogenesis when secreted by cells." (PMID 25428918, 2014). "Found that MSC-AS1 enhanced hepatocellular carcinoma progression by enhancing PGK1 expression." (PMID 33819916, 2021). "It has been reported that PGK1 is an independent prognostic indicator of hepatocellular carcinoma (HCC) and may be a new therapeutic target for HCC." (PMID 37723547, 2023). "In hepatocellular carcinoma, lncRNA MVIH inhibits the secretion of phosphoglycerate kinase 1 (PGK1) through a direct interaction, which prevents the inhibitory effects of PGK1 on tumor angiogenesis." (PMID 36010595, 2022). "As for hepatocellular carcinoma, there is a hypothesis that c-MYC mainly regulates controlling PGK1 expression." (PMID 28749413, 2017). "GPR50, significantly upregulated in hepatocellular carcinoma (HCC) patients and the CBRH-7919 cell line, promotes HCC progression by enhancing cell proliferation, migration, and autophagy, mediated through interactions with CCT6A and PGK1, suggesting GPR50 as a potential therapeutic target for HCC." (PMID 39315094, 2024). "A recent study demonstrated that PGK1 expression is repressed by MVIH, a long noncoding RNA (lncRNA) that activates tumour-induced angiogenesis in hepatocellular carcinoma (HCC)." (PMID 37723547, 2023).
pancreatic cancer (23 papers, 2009 to 2025). "KIF15 is responsible for USP10-induced PGK1 deubiquitination, thereby enhancing the glycolytic capacity for pancreatic tumor growth." (PMID 40087774, 2025). "In SMAD4 deletion-induced pancreatic cancers, there is an upregulation of PGK1 expression, leading to enhanced aerobic glycolysis and increased invasive behaviors." (PMID 38686046, 2024). "NFAT5 is upregulated in pancreatic cancer cells and promotes aerobic glycolysis by inducing phosphoglycerate kinase 1 (PGK-1)." (PMID 36077186, 2022). "For example, NFAT5 was proved to conduce to the glycolytic phenotype rewiring and pancreatic cancer progression through transcription of PGK1." (PMID 32863773, 2020). "In our study, we demonstrated that NFAT5 contributes to glycolytic phenotype rewiring and pancreatic cancer progression via transcription of PGK1." (PMID 31827081, 2019). "In pancreatic cancers, PGK1 is secreted into the bloodstream, and studies have shown increased levels of serum PGK1." (PMID 19221597, 2009). "For instance, in pancreatic cancer, PGK1 can translocate into the nucleus and participate in the regulation of gene transcription under SMAD4 mutation, thereby inducing the invasion capabilities of pancreatic cancer cells." (PMID 40534132, 2025). "Thus, inhibiting PGK1 S256 phosphorylation may enhance pancreatic cancer’s radiotherapy sensitivity." (PMID 41213904, 2025). "Our study demonstrated that NFAT5 is upregulated in pancreatic cancer cells, and NFAT5 facilitates PDAC cell survival via contributing to the Warburg effect by transcription of PGK1." (PMID 31827081, 2019). "In addition to the reprogramming of glycolysis, mutant KRAS signaling contributes to phosphoglycerate kinase 1 (PGK1) translocation in mitochondrion, leading to PDHK1 phosphorylation and Oxphos restriction in pancreatic cancer cells." (PMID 37187730, 2023). "In addition to the regulation of glycolysis, mutant KRAS signaling stimulates mitochondrial translocation of phosphoglycerate kinase 1 (PGK1), leading to phosphorylated PDHK1 and restricted OXPHOS in pancreatic cancer cells." (PMID 32122374, 2020). "Therefore, the results suggested that PGK1, ALDOA, and LDHA may play important synergistic roles for P4HA1 in pancreatic cancer." (PMID 33415167, 2020).
colorectal cancer (20 papers, 2006 to 2025). A primary or metastatic malignant neoplasm that affects the colon or rectum. "Phosphoglycerate kinase 1 (PGK1), which was consistently associated with poor prognosis in training cohorts also displayed a strong dependency in colorectal cancer cell lines (data from the cancer dependency map project)." (PMID 37654625, 2023). "Intriguingly, reconstituting endogenously PGK1- or MORC2-depleted HT29 colorectal cancer cells with the phosphorylation-defective mutants PGK1-S256A or MORC2-S711A, respectively, conferred heightened radiosensitivity relative to WT counterparts." (PMID 41213904, 2025). "Unsurprisingly, PGK1 also functions in concert with ALDOC to regulate glycolysis-related parameters as well as malignant phenotypes of colorectal cancer cells." (PMID 40518543, 2025). "In colorectal cancer, however, PGK1 is upregulated, where its O-GlcNAcylation facilitates mitochondrial translocation." (PMID 41488637, 2025). "In colorectal cancer, beyond PGK1 modification, O-GlcNAcylation of c-Myc suppresses the TCA cycle by upregulating the transcription of PDK2." (PMID 41488637, 2025). "In conclusion, this study identified ALDOC/PGK1 axis as a key promotor of colorectal cancer development through inducing glycolysis." (PMID 40518543, 2025). "The interaction between RPS24c mRNA and LncRNA MVIH activates colorectal cancer angiogenesis by inhibiting the secretion of PGK1." (PMID 34616746, 2021). "Phosphoglycerate kinase 1 (PGK1) O-GlcNAcylation levels are significantly upregulated in colorectal cancer; O-GlcNAcylation activates PGK1 activity to upregulate the TCA cycle and results in lactate production." (PMID 35004688, 2021). "Furthermore, we observed that the PGK1-mediated MORC2-S711 phosphorylation also promotes radioresistance in colorectal cancer." (PMID 41213904, 2025). "Moreover, PGK1 mRNA expression was consistently significantly elevated in colorectal cancer tumors compared with matched normal colonic tissue in 13 from 14 cohorts." (PMID 37654625, 2023). "Mir-548c-5p may play an anti-cancer role by targeting PGK1 to inhibit the generation of inflammatory cytokines and proliferation in colorectal cancer cells." (PMID 33584825, 2021). "Upon mitochondrial entry, PGK1 acts as a protein kinase to phosphorylate PDK1, thereby inhibiting PDH, reducing TCA flux, and enhancing colorectal cancer cell proliferation." (PMID 41488637, 2025). "Therefore, PGK1 might represent a potential therapeutic target for colorectal cancer." (PMID 37654625, 2023). "Meanwhile, JMJD2D has been shown to increase the transcriptional activity of phosphoglycerate Kinase 1 (PGK1) by interacting with HIF1-α, thus enhancing glycolysis to facilitate the progression of colorectal cancer." (PMID 35558079, 2022). "In colorectal cancer (CRC), cellular experiments have proven that downregulated miR-548c-5p restrains cancer cell growth and reproduction of inflammatory cytokines by directly targeting PGK1." (PMID 34860853, 2021). "Interestingly, we have previously found that miR-638 may be involved in the regulation of glucose metabolism in colorectal cancer by targeting HIF-1α and PGK1." (PMID 29069781, 2017).
ovarian cancer (17 papers, 2010 to 2025). A primary or metastatic malignant neoplasm involving the ovary. "The PGK1 expression level was an independent risk factor for the survival and prognosis of patients with ovarian cancer." (PMID 34277429, 2021). "SLC16A3, PFKP, and PGK1, which were highly expressed in ovarian cancer tissues in two databases and associated with poor prognosis, were selected for further analysis." (PMID 34277429, 2021). "Further biological functional experiments confirmed that inhibition of PGK1 expression in ovarian cancer cells can reduce the EMT process, resulting in loss of cell migration and invasion ability." (PMID 34277429, 2021). "COX regression model analysis indicated that high PGK1 expression was an independent risk factor affecting the survival and prognosis in patients with epithelial ovarian cancer." (PMID 34277429, 2021). "PGK1 overexpression was confirmed to be associated with multidrug resistance in ovarian cancer." (PMID 34277429, 2021). "Therefore, PGK1 has the greatest correlation with prognosis in patients with ovarian cancer and is closely associated with tumorigenesis and progression." (PMID 34277429, 2021). "Among the highly expressed glycolysis-related genes, high GPI expression was associated with poor prognosis of post-progression survival (PPS) and overall survival (OS) in patients with ovarian cancer, and high expression of PGK1 was associated with poor PFS and PPS." (PMID 34277429, 2021). "However, the regulation of PGK1 in ovarian cancer cells and the underlying molecular mechanisms are still poorly understood." (PMID 31649264, 2019). "Han RL reported that miR‐383 suppressed the expression level of LDHA, an mRNA highly correlated with PGK1, by directly binding to its 3'‐untranslated region and thus silenced aerobic glycolysis in ovarian cancer cells." (PMID 34668665, 2021). "Kaplan-Meier plotter analysis indicated that among the highly expressed glycolysis genes, SLC16A3, HK2, GPI, PFKP, and PGK1, were closely associated with poor PFS, PPS, or OS in patients with ovarian cancer." (PMID 34277429, 2021). "Compared with the control group, knockdown of PGK1 significantly reduced the migration and invasion ability of ovarian cancer." (PMID 34277429, 2021). "Based on the results showing the role of PGK1 in glycolysis of ovarian cancer, the cBioPortal database was used to analyze the correlation between PGK1 expression and other glycolysis-related genes in ovarian cancer." (PMID 34277429, 2021). "The present study included a large number of clinical specimens to confirm the expression level and prognostic value of PGK1 in ovarian cancer." (PMID 34277429, 2021). "The function of PGK1 in ovarian cancer was clarified and the value of NG52 as a targeted drug was proposed." (PMID 34277429, 2021). "Immunochemistry assays showed that PGK1 was highly expressed in epithelial ovarian cancer, especially in mucinous carcinoma." (PMID 34277429, 2021). "Multivariate analysis indicated PGK1 expression level (P = 0.035) and FIGO stages (P = 0.003) were independent risk factors affecting the survival and prognosis of patients with epithelial ovarian cancer." (PMID 34277429, 2021). "Relationships between PGK1 expression in epithelial ovarian cancer and clinicopathological parameters." (PMID 34277429, 2021). "A total of 103 patients with epithelial ovarian cancer were divided into high PGK1 expression group (++/+++) and low PGK1 expression group (-/+)." (PMID 34277429, 2021). "Weather PDK1 can be phosphorylated by PGK1, leading to ovarian cancer tumorigeneses and metastasis will be examined in future studies." (PMID 32071289, 2020). "Third, the expression of ACLT6A was positively correlated with PGK1 in clinical samples of ovarian cancer and tumor xenografts." (PMID 31649264, 2019). "Collectively, our data provide a new mechanism for tumorigenicity of ACTL6A and reveal a previously unappreciated role for FSH/ACTL6A/PGK1 axis facilitates glycolysis in ovarian cancer." (PMID 31649264, 2019).
ovarian cancer (continued). "Our study further reveals that silencing of ACTL6A attenuates FSH-driven ovarian cancer glycolysis by downregulating PGK1 expression." (PMID 31649264, 2019). "Western blotting analysis showed that stimulation of FSH enhanced PGK1 expression in ovarian cancer cells, which was further eliminated by downregulation of ACTL6A." (PMID 31649264, 2019). "Altered ACTL6A expression inhibits the tumorigenicity of ovarian cancer cells in vivo by downregulating PGK1." (PMID 31649264, 2019). "We identified the critical roles of ACTL6A and PGK1 expression in glycolysis in ovarian cancer and the novel function for ACTL6A in FSH-induced glycolysis." (PMID 31649264, 2019). "Next, we evaluated the relationship between ACTL6A and PGK1 in ovarian cancer tissues by IHC analysis." (PMID 31649264, 2019). "Consistent with the protein level, the mRNA expression of ACLT6A was likewise positively correlated with PGK1 in ovarian cancer cohort from TCGA (R2 = 0.0953, p < 0.001)." (PMID 31649264, 2019). "PGK1 is the first ATP-producing enzyme in glycolysis; therefore, it plays a key role in cellular redox balance, and was recently proposed as a molecular target for antiglycolytic therapy of ovarian cancer." (PMID 37958751, 2023). "We hypothesize that PGK1 will become a powerful target for anti-glycolysis therapy in ovarian cancer." (PMID 34277429, 2021). "Similarly, when PGK1 was knocked down, the formed colonies of ovarian cancer cells were markedly reduced." (PMID 34277429, 2021). "Cell experiments confirmed that inhibiting PGK1 expression in ovarian cancer cells could reduce the epithelial-mesenchymal transition (EMT) process, resulting in loss of cell migration and invasion ability." (PMID 34277429, 2021). "Results showed that NG52 attenuated the kinase activity of PGK1 in ovarian cancer cells." (PMID 34277429, 2021). "In addition, we evaluated the significance of PGK1 as an attractive molecular target in the anti-glycolytic treatment of ovarian cancer and proposed the therapeutic effect of NG52 as a PGK1 inhibitor." (PMID 34277429, 2021). "Immunochemistry assays confirmed that PGK1 was highly expressed in ovarian cancer." (PMID 34277429, 2021). "Therefore, PGK1 can be considered as an attractive molecular target for anti-glycolytic therapy of ovarian cancer." (PMID 34277429, 2021). "Thus, the present study provides mechanistic and clinical evidence supporting a model that ACTL6A induces glycolysis in ovarian cancer cells via PGK1." (PMID 31649264, 2019). "We found a positive correlation between ACTL6A and PGK1 expression in ovarian cancer tissues." (PMID 31649264, 2019). "While, there have been several lines of evidence indicating that PGK1 overexpression could induce the chemoresistance of breast and ovarian cancer cells." (PMID 30953511, 2019). "Here we found that ACTL6A-mediated glycolysis in ovarian cancer cells via regulation of PGK1." (PMID 31649264, 2019). "Therefore, PGK1 is an attractive molecular target for anti-glycolytic therapy of ovarian cancer." (PMID 34277429, 2021). "Therefore, PGK1 showed the greatest prognostic value for patients with ovarian cancer." (PMID 34277429, 2021). "Previous research demonstrated that follicle-stimulating hormone (FSH)-enhanced glycolysis in ovarian cancer contained a high level of ACTL6A and that ACTL6A increased phosphoglycerate kinase 1 (PGK1), therefore aiding the proliferation of ovarian cancer." (PMID 36768349, 2023). "A large number of clinical specimens were used to screen out phosphoglycerate kinase 1 (PGK1), which showed the strongest correlation with the prognosis of ovarian cancer patients." (PMID 34277429, 2021). "Knockdown of PGK1 in ovarian cancer cells decreased ECAR and increased OCR, reflecting the positive role of PGK1 in the regulation of aerobic glycolysis." (PMID 34277429, 2021). "Due to the high PGK1 expression in ovarian cancer, the anti-proliferative effect of NG52 in various ovarian cancer cell lines was investigated." (PMID 34277429, 2021).
ovarian cancer (continued). "However, the prognostic value and mechanism of PGK1 in ovarian cancer remain unclear." (PMID 34277429, 2021). "In the present study, we explored the role of PGK1 in epithelial-mesenchymal transition (EMT) process and immune evasion in ovarian cancer." (PMID 34277429, 2021). "Therefore, among glycolysis-related genes, PGK1 may play the most critical role in the glycolysis process of ovarian cancer, and targeted drugs for PGK1 may effectively improve the survival of patients with ovarian cancer." (PMID 34277429, 2021). "Phosphoglycerate kinase 1(PGK1) expression can be upregulated by overexpressing ACTL6A, but PGK1 expression is downregulated by ACTL6A knockdown, which impacts the glycolysis and growth of ovarian cancer cells." (PMID 40755753, 2025). "In ovarian cancer cell lines, B7-H3 knockout resulted in a decreased level of glycolysis and reduced the expression of lactate dehydrogenase A (LDHA), phosphoglycerate kinase 1 (PGK1) and HIF-1α, which suggests that B7-H3 promotes glycolysis." (PMID 36284349, 2022). "In view of PGK1 was the most altered gene, we chose PGK1 as the target gene and try to investigate whether ACTL6A-enhanced glycolysis in ovarian cancer was dependent upon PGK1." (PMID 31649264, 2019). "Therefore, PGK1 may affect the recruitment of neutrophils by regulating the level of CXCL8, leading to the progression of ovarian cancer." (PMID 34277429, 2021). "Interestingly enough, the increased acetylation level of PGK1 at K323 may promote its enzyme activity and exacerbate the EMT process in ovarian cancer cells." (PMID 34899851, 2021).